OCA2 (OCA2 melanosomal transmembrane protein)
Diseases named in the same sentence as OCA2 in open-access papers (continued):
Sharing a sentence is not in itself a finding about the gene and the disease.
albinism (continued). "The oculocutaneous albinism (oca2), matp/aim1, and slc24a5 genes function at the first step of the melanin synthesis pathway and presumably make L-tyrosine available for conversion to L-DOPA by tyrosinase." (PMID 24282555, 2013). "The region of high FST on the q‐arm contained 15 genes and included OCA2, previously suggested to be involved in the variation in fur colouration within the species, as deletions within this gene can lead to albinism in cavefish." (PMID 41431222, 2026). "Hence, individuals with TYR- and OCA2-related albinism exhibit comparable levels of visual impairment and overlapping skin and hair pigmentation phenotypes." (PMID 40996958, 2025). "Analyses of common polymorphisms of known albinism genes revealed the presence of the phenotype-modifying R305W OCA2 variant in patient No. 16, but not in his mother." (PMID 38279271, 2024). "First of all, this study demonstrates that the sequencing of whole genes, as we did here with our current diagnostic panel that contains the entirety of five major albinism genes (TYR, OCA2, SLC45A2, GPR143 and HPS1), is instrumental in identifying deep intronic splice variants in these genes." (PMID 39201349, 2024). "The gene responsible for albinism is oculocutaneous albinism 2 (oca2), which was identified initially through QTL mapping, and confirmed through functional studies, including generation of surface fish with mutations in this gene and finding that the resulting animals lacked melanin pigmentation." (PMID 39606270, 2023). "Broadly, we found that pigmentation did not associate with nearly all traits tested (with the exception of eye size and locomotor activity), suggesting that loss of oca2 function is relatively specific to albinism and does not impact the behaviors tested." (PMID 35924750, 2022). "Novel and reported TYR, OCA2 and HPS-1 variants identified in albinism families in this study." (PMID 35328057, 2022). "OCA2 is by far the most common type of albinism seen in Africa." (PMID 36353393, 2022). "During melanosome maturation, the melanosomal pH is modulated owing to the activity of membrane transport proteins such as SLC45A2, OCA2/P, TPC2, the Cl−/H+ exchanger CLC-7 mutated in a subset of albinism patients and possibly other still unidentified Ca2+ channels." (PMID 34921635, 2021). "OCA2 (OMIM #203200) caused by mutations in the OCA gene, formerly known as the “P” gene, is the most common form of albinism worldwide; the estimated prevalence is 1 in 10,000 in the African American population, 1 in 30,000 in Caucasians, and closer to 1 in 3,900 in southern parts of Africa." (PMID 33808351, 2021). "Only three patients (six eyes) with FH were included, all with OCA2-associated albinism; thus, findings may not generalize to other genetic or acquired causes of FH." (PMID 41462409, 2025). "However, the evolutionary cause(s) of albinism, which is itself controlled by the single oca2 gene with a QTL of negative polarity, is still uncertain." (PMID 24282555, 2013). "Analysis of VA of FHONDA compared to the different subtypes of albinism showed a significantly better VA in OCA1 and OCA2 (median = 0.5 logMAR, IQR = 0.3–0.7, P= 0.004, and median = 0.5 logMAR, IQR = 0.2–0.7, P = 0.006), respectively)." (PMID 35029636, 2022). "In this study, we described the genotypic and phenotypic characteristics of the rare FHONDA syndrome and compared it to the phenotype of the most common types of albinism, OCA1, OCA2, and OA1." (PMID 35029636, 2022). "As the major enzymes participated in mammals albinism, TYR, TYRP1, OCA2 and SLC45A2 also exhibited down regulation in albino pigmented P. olivaceus individuals." (PMID 28777813, 2017). "We screened 172 patients with clinical signs of albinism for sequence variations in genes most prevalent in human OCA and OA (TYR, OCA2, and GPR143)." (PMID 21541274, 2011).
albinism (continued). "In the present study, we analyzed 122 heterozygous patients with albinism either by whole genome sequencing or by the use of our next-generation sequencing panel that includes the entire sequence of the TYR, OCA2, SLC45A2, GPR143 and HPS1 genes (exons, introns, flanking sequences)." (PMID 39201349, 2024). "Genetic analysis revealed seven coding variants in the cohort that were presumed to be albinism-causing and, to the authors’ knowledge, have not previously been reported: three in TYR, one in OCA2, one in TYRP1, one in SLC45A2, and one in GPR143." (PMID 38441889, 2024). "This study aimed to compare the rates of rare alleles in albinism genes in patients with AHM, PM only, or with no melanoma history and found differences in rates of TYR/OCA1 and OCA2 variants." (PMID 32966289, 2020). "The most common cause of foveal hypoplasia is albinism, but no mutations were identified in SLC45A2, TYR, TYRP1, GPR143, OCA1, OCA2, OCA3, or OCA4." (PMID 28546991, 2017). "As albinism is an obvious trait, we assessed fish injected with TALENs targeted to oca2 exon 9 for evidence of mosaic absence of melanin pigmentation." (PMID 25774757, 2015). "Autosomal recessive ocular albinism (AROA) is a term that has been used for patients with albinism with an ocular phenotype caused by mutations in TYR, OCA2, TYRP, SLC45A2, SLC24A5, or LRMDA (OCA1-7), but without a clearly defined boundary between calling a phenotype OCA or AROA." (PMID 38555393, 2024). "Albinism occurs from the deletion of OCA2, but albinism is not present in all cases." (PMID 35406524, 2022). "Twenty-nine (30%) patients had albinism caused by variants in TYR gene, 23 (24%) had OCA2, 14 (15%) had x-linked albinism with variants in GPR143 gene, 13 (13%) had other genetically verified types of albinism and in the remaining 17 (18%) the genetic cause of albinism could not be established." (PMID 38136112, 2023).
oculocutaneous albinism (43 papers, 2006 to 2026). Oculocutaneous albinism (OCA) describes a group of inherited disorders of melanin biosynthesis characterized by a generalized reduction in pigmentation of hair, skin and eyes and variable ocular findings including nystagmus, reduced visual acuity and photophobia. "Genetic testing confirmed the presence of pathological variants of the OCA2 gene, leading to a diagnosis of oculocutaneous albinism." (PMID 41523963, 2026). "These include OCA2, also significantly associated in our GWAS analysis, which has a prior association to oculocutaneous albinism." (PMID 36848389, 2023). "The most prevalent form of oculocutanous albinism is oculocutanous albinism type 2 in which mutations in the OCA2 gene cause changes in the transmembrane protein p protein (Oca2) thereby impacting melanin production." (PMID 37431738, 2023). "Individuals with BCM, BED, RPGR-associated disease, and OCA2-associated oculocutaneous albinism showed significantly increased odds for having an AL of 26 mm or greater." (PMID 35704304, 2022). "Truncations occurring at similar positions in the OCA2 protein have been identified in humans and are associated with oculocutaneous albinism." (PMID 36260636, 2022). "Our results were beneficial for diagnosis and precision clinical management for OCA2-related disorder, and this study expanded the mutation spectrum of oculocutaneous albinism." (PMID 34707637, 2021). "In this study, we collected 28 oculocutaneous albinism patients with compound heterozygous or homozygous OCA2 variants identified by sequencing." (PMID 34707637, 2021). "These include rs1800407 and rs1042602, at loci previously associated with oculocutaneous albinism (in OCA2 and TYR respectively)." (PMID 33979322, 2021). "The human HERC2 gene locus is upstream of that of the OCA2 gene (mutated in oculocutaneous albinism) and certain HERC2 SNPs can interfere OCA2’s expression thus affecting eye, skin, and hair pigmentation." (PMID 31447701, 2019). "OCA1 and OCA2 are caused by mutations of the TYR and OCA2 genes, respectively, which are responsible for most oculocutaneous albinism." (PMID 31196117, 2019). "The distribution of mutational OCA genes was slightly shifted, OCA2 is the most common type in our oculocutaneous albinism population in Guangxi, China." (PMID 31196117, 2019). "We therefore conclude that the observed oculocutaneous albinism in German Spitz is most likely caused by the identified variant in the 5’-splice site of the first intron of the canine OCA2 gene." (PMID 28973042, 2017). "In conclusion, we identified a variant in the conserved 5’-splice site of the first intron of the canine OCA2 gene as most likely cause for the observed oculocutaneous albinism in a Giant Spitz family." (PMID 28973042, 2017). "In this study, we identified a splice site variant in the canine OCA2 gene as most likely cause for an oculocutaneous albinism phenotype in dogs." (PMID 28973042, 2017). "Based on our revised canine OCA2 full-length sequence, the candidate causative variant for oculocutaneous albinism in dogs should be designated OCA2:LT844587.1:c.-45+2T>G." (PMID 28973042, 2017). "Another missense mutation, p.Ala787Val, affecting the same codon of the OCA2 gene as p.Ala787Thr, was also reported to cause oculocutaneous albinism, further confirming the necessity of the alanine residue at this position for proper OCA2 protein function." (PMID 22734612, 2012). "Pathogenic variants in the OCA2 gene result in oculocutaneous albinism." (PMID 40996958, 2025). "The loss of function of OCA2, a key player in pigmentation, results in oculocutaneous albinism." (PMID 40996958, 2025). "OCA2 is a key regulator of melanin synthesis, affecting both eumelanin and pheomelanin production, with a splice site variant in the canine OCA2 gene associated with the oculocutaneous albinism phenotype in dogs." (PMID 38791725, 2024).
oculocutaneous albinism (continued). "Of 19 diseases, 10 had >10 participants: ABCA4 retinopathy; CNGB3- and CNGA3-associated achromatopsia; RPGR-associated disease; RPE65-associated disease; blue cone monochromacy (BCM); Bornholm eye disease (BED); TYR- and OCA2-associated oculocutaneous albinism; and GPR143-associated ocular albinism." (PMID 35704304, 2022). "High frequency (30.8%) of mutation c.1832 T > C in our patients, which suggest that L611P may be a common P gene mutation associated with the typical OCA2 phenotype in oculocutaneous albinism population in Guangxi, China." (PMID 31196117, 2019). "OCA2 is one of eight non-syndromic autosomal recessive oculocutaneous albinism (OCA) loci and is the second most common cause of OCA worldwide." (PMID 41905947, 2026). "Oculocutaneous albinism type 2 (OCA2) is one of the most common forms of OCA, caused by OCA2 mutations." (PMID 40313672, 2025). "Oculocutaneous albinism (OCA) is a genetic disorder caused by mutations in genes involved in melanin synthesis, including Tyr (OCA-1), Oca2 (OCA-2), Tyrp1 (OCA-3), and Slc45a2 (OCA-4)." (PMID 40286213, 2025). "As mutations in the TYR and OCA2 genes account for the majority of OCA cases, we have analyzed and examined the TYR and OCA2 genes in four Chinese families with oculocutaneous albinism in the present study, identifying the causative mutations in each." (PMID 25919014, 2015). "Among the ion channel and transporters genes involved in pigmentation disorders three are altered in subtypes of oculocutaneous albinism (OCA) (OCA2, SLC45A2, and SLC24A5, in OCA 2, 4 and 6 respectively)." (PMID 39809949, 2025). "OCA2 (oculocutaneous albinism type II) is a type of oculocutaneous albinism, and its occurrence rate makes it the most common in the world (1:39,000)." (PMID 38396851, 2024). "The patient was referred for genetic testing and the results confirmed the diagnosis of tyrosinase-positive oculocutaneous albinism (OCA2)." (PMID 37790023, 2023). "Only the well-described oculocutaneous albinism variants, TYR and OCA2, were significantly associated with skin colour (P = 2.19 x 10-4 & 2.31 x 10-3, respectively)." (PMID 33979322, 2021). "Mutations of the oculocutaneous albinism two gene (OCA2; OMIM 611409) are associated with OCA type 2 (OCA2)." (PMID 28629449, 2017). "Among the four genes under-expressed in Duroc, two genes are specifically known to be involved in skin coloration: KIT (v-kit Hardy-Zuckerman 4 feline sarcoma viral oncogene homolog or Dominant white locus in pigs;) and OCA2 (oculocutaneous albinism II)." (PMID 26651482, 2015). "Mutations in TYR, OCA2, TYRP1, and SLC45A2 are mainly responsible for causing oculocutaneous albinism." (PMID 25093188, 2014). "OCA2 was first identified in 1993, in a patient with tyrosinase-positive oculocutaneous albinism." (PMID 34707637, 2021). "Oculocutaneous albinism (OCA) is a recessive condition caused mainly by mutations in the TYR and OCA2 genes involved in skin pigmentation." (PMID 39556609, 2024). "Tyrosinase-positive oculocutaneous albinism (OCA, type II, OCA2) is an autosomal recessive genetic disease in which the biosynthesis of melanin decreases in the skin, hair, and eyes." (PMID 34707637, 2021). "Oculocutaneous albinism (OCA) is a genetically inherited autosomal recessive condition and OCA2, tyrosine-positive albinism, is the most prevalent type found throughout Africa." (PMID 16916463, 2006).
melanoma (38 papers, 2007 to 2025). A malignant, usually aggressive tumor composed of atypical, neoplastic melanocytes. "Our OCA2-mutated patient developed three melanomas, which showed an atypical pattern with irregular polychromatic pigmentation, dark areas alternating with lighter areas, and pinkish and regression areas." (PMID 37568588, 2023). "Individuals with OCA2 mutation are at a higher risk of developing UV-induced skin cancers including melanoma." (PMID 36483028, 2022). "Variants highly associated with melanoma were also found in three other regions: oculocutaneous albinism 2 (OCA2, chr15:27670078–28337214), E-cadherin (CDH1, chr16:68528729–68923897) and cyclin D1 (CCND1, chr11:69210414–69803433)." (PMID 35357426, 2022). "In co-segregation analysis of the extended pedigree, both of these OCA2 deleterious alleles were analyzed as melanoma risk variants, with an OR of 6.55." (PMID 32966289, 2020). "In a recent report of a multi-gene panel screening of Dutch non-CDKN2A/CDK4 melanoma families, 9 rare pathogenic variants of OCA2 were found." (PMID 32966289, 2020). "The OCA2 hypomorphic allele p.V443I was more common in melanoma cases (1.8%) than controls (1.0%, X2P = 0.02), and more so in amelanotic/hypomelanotic melanoma (4.4%, X2P = 0.007)." (PMID 32966289, 2020). "The greatest contributor to normal variation in eye color is a common intronic single nucleotide polymorphism, rs12913832 in OCA2, that also affects skin color, but has a disproportionately small magnitude of effect on melanoma risk." (PMID 32966289, 2020). "TYR and OCA2 deleterious alleles in pigmented melanoma and amelanotic/hypomelanotic melanoma patients." (PMID 32966289, 2020). "HERC2/OCA2 gene non-coding allele/haplotype in pigmented melanoma and amelanotic/hypomelanotic patients." (PMID 32966289, 2020). "TYR variants and OCA2 p.V443I in control vs any melanoma case and amelanotic/hypomelanotic melanoma patients." (PMID 32966289, 2020). "As lighter skin color is recognized as a risk factor for melanoma this would provide a plausible explanation for the raised frequency of TYR and OCA2 p.V443I albinism/deleterious gene allele carriers in melanoma cases." (PMID 32966289, 2020). "Deleterious variants in TYR/OCA1 were more common in AHM melanoma cases than in PM cases and the same was true for the OCA2 hypomorphic allele p.V443I." (PMID 32966289, 2020). "In contrast, the MC1R (chromosome 16) and HERC2/OCA2 (chromosome 15) loci, both of which affect pigmentation, lose their significance, implying that they influence melanoma risk through their effects on pigmentation phenotypes." (PMID 28973033, 2017). "OCA2 polymorphisms are associated with differences in eye color, however, OCA2-linked differences in melanoma susceptibility persist after controlling for eye color." (PMID 22615734, 2012). "In humans polymorphisms in the human homolog of the Oca2 gene are associated with genetic susceptibility to melanoma." (PMID 22615734, 2012). "Variations in OCA2 have been associated with susceptibility to melanoma, which has also been reported to occur with increased frequency among PD cases." (PMID 19772629, 2009). "Therefore, genetic mutations of the OCA2 channel lead to acidic melanosomal pH, hypopigmentation due to decreased eumelanin synthesis, and increased risk for melanoma." (PMID 36483028, 2022). "OCA2*R419Q is thought to modify the penetrance of the OCA2 locus and may affect the risk of melanoma; therefore, our data may support a role for melanosomal pH in melanoma genesis." (PMID 34361043, 2021). "Individuals with darker hair may still be heterozygous carriers of deleterious TYR and OCA2 p.V443I albinism genes that will have effects on melanogenesis in the skin and so increase the risk of these hypopigmented melanomas." (PMID 32966289, 2020). "Mutations in OCA2 gene associate with oculocutaneous albinism type II and melanoma." (PMID 26870082, 2016).